KEAP1 (kelch like ECH associated protein 1)
Diseases named in the same sentence as KEAP1 in open-access papers (continued):
Sharing a sentence is not in itself a finding about the gene and the disease.
goiter (8 papers, 2016 to 2025). Enlargement of the thyroid gland usually caused by lack of iodine in the diet, hyperthyroidism, or thyroid nodules. "Clinical findings on the probands of 5 families with abnormalities of KEAP1 showed that all variants were heterozygous, and the age of goiter onset ranged between 13 and 37 years." (PMID 39373520, 2025). "In mice, genetic activation of Nrf2 signaling secondary to decreased expression of Keap1 causes age-dependent subclinical hypothyroidism and goiter." (PMID 35624879, 2022). "We also showed that decreased expression of Keap1, which is associated with constitutive activation of Nrf2 signaling, can cause goiter with a tendency for hypothyroidism." (PMID 32961913, 2020). "She had a family history of goiter and carried a germline mutation (R483H) in KEAP1 gene." (PMID 27703446, 2016). "Therefore, in a recent study we used Keap1KD mice to verify whether decreased Keap1 levels can cause goiter." (PMID 33158045, 2020). "Some reports on mice and humans showed the involvement of the Keap1/Nrf2 system in goiter formation and that the gene-based over-activation of Nrf2 in the thyroid can induce goiter formation with variable phenotypic characteristics." (PMID 37371907, 2023). "Over the last few years, multiple links have emerged between the Keap1/Nrf2 pathway and thyroid physiology, as well as various thyroid pathologies, including autoimmunity, goiter, hypothyroidism, hyperthyroidism, and cancer." (PMID 33158045, 2020). "It is reasonable to assume that the germline Keap1 mutation may determine Nrf2 activation in the thyroid, as in all other tissues; however, no diseases other than goiters were described in the patient affected, and this intriguing aspect needs to be investigated further." (PMID 37371907, 2023). "Of the 3 members without multinodular goiter, 2 (R483H I-6 and III-2) harbored no mutation in KEAP1, and 1 (R483H III-1) had the same mutation as the proband but had no goiter or nodular lesions at age 22 at follow-up." (PMID 39373520, 2025).
malignant glioma (8 papers, 2012 to 2025). A grade III or grade IV glioma arising from the central nervous system. "On the other hand, some cases of malignant glioma are characterized by an increase of KEAP-1 promoter methylation which leads to an upregulation of KEAP-1 transcription and a consequent higher degradation of Nrf2." (PMID 38666930, 2024). "Frequent promoter hypermethylation and correlated down-regulation of the Keap1 expression were observed in malignant gliomas and contributed to the resistance to radiotherapy." (PMID 27029077, 2016). "The hypermethylation of the promoter region of KEAP1 gene has been identified in cancer cells generated in lung, prostate, malignant glioma, and colorectal cancers." (PMID 23272301, 2012).
steatosis (8 papers, 2013 to 2025). Increased lipid within the cytoplasm of cells. "It is well-established that endogenous Keap1 level plays an important role in controlling Nrf2 activity, and that knock-down of Keap1 gene can boost Nrf2 activity and alleviate oxidative stress and steatosis induced by fasting." (PMID 32365333, 2020). "Previously we have shown that Nrf2 over-activation in hepatocytes after Keap1 deletion resulted in diminished hepatocyte steatosis and progression to steatohepatitis." (PMID 32365632, 2020). "Enhanced Nrf2 activity via Keap1-KD decreased fasting-induced steatosis, pointing to an important function of Nrf2 on lipid metabolism under the condition of nutrient deprivation." (PMID 24224011, 2013). "Besides, Keap1-KD mice fed a long-term (24 weeks) HFD showed hepatic inflammation and steatosis, without affecting the protein level of Glut4." (PMID 33066023, 2020).
ulcerative colitis (8 papers, 2018 to 2025). An inflammatory bowel disease involving the mucosal surface of the large intestine and rectum. "Overall, the synergic combination of Keap1-Nrf2 inhibitors and H2S donors has the potential for ulcerative colitis treatment, and molecular hybridization may be a promising strategy for the therapy of multifactorial inflammatory disease." (PMID 37237928, 2023). "Accordingly, P. americana can reduce DSS-induced ulcerative colitis (UC) by activating the Keap1/Nrf-2 pathway, promoting tight junction protein expression and improving intestinal barrier function, and both P. brevitarsis larvae and M. domestica larvae have anti-inflammatory effects." (PMID 35651499, 2022). "Epoxymicheliolide alleviates ulcerative colitis by covalently targeting TAK1 and Keap1 to inhibit NF-κB-mediated inflammation and activate the Nrf2 antioxidant pathway." (PMID 41158126, 2025).
asthma (7 papers, 2021 to 2024). "Inhibition of inflammation and oxidative stress are two of Ech’s therapeutic actions in managing asthma by modulating the Keap1/Nrf2 signaling pathway." (PMID 37623736, 2023). "The present findings reveal the therapeutic potency of β-END in regulating asthma by Keap-1 independent regulation of Nrf-2 activity." (PMID 37524754, 2023). "Inhibition of inflammation and oxidative stress are two of echinochrome’s therapeutic actions in managing asthma by modulating the Keap1/Nrf2 signaling pathway." (PMID 37623736, 2023). "Data were normalized in order to evaluate the effects of vitamin E. The levels of Nrf2, HO‐1, and IkB were restored; in contrast, the levels of NFκB and Keap1 were decreased after vitamin E treatment in the lung tissues of old asthma mice compared to the young asthmatic mice." (PMID 34089243, 2021). "Several studies have shown that many molecular signaling pathways, such as JAK/STAT/MAPK, NF-κB, Wnt/β-catenin, PI3K/Akt, JNK, Fas/FasL, TLRs/MyD88, and Keap1/Nrf2/ARE, are important in the pathophysiology of asthma." (PMID 34446024, 2021).
clear renal cell carcinoma (7 papers, 2017 to 2024). "In clear-cell renal cell carcinoma (ccRCC), the epigenetic modulation of KEAP1 was shown to be the leading mechanism of KEAP1 deregulation, and it was able to strongly predict patient survival." (PMID 32971994, 2020). "In clear renal cell carcinoma (ccRCC), the epigenetic modulation of KEAP1 was shown to be the leading mechanism of KEAP1 deregulation (48.6%), thus supporting a driver role of the KEAP1/NRF2 axis in renal cancer." (PMID 29643973, 2018). "Furthermore, dipeptidyl peptidase 9 (DPP9) competes with NRF2 for binding to KEAP1 in an enzyme-independent manner, thereby disrupting the KEAP1-NRF2 signaling pathway and influencing tumorigenesis and drug resistance in clear cell renal carcinoma (ccRCC)." (PMID 39544949, 2024).
emphysema (7 papers, 2009 to 2025). "Previous studies on this topic indicated that the decrease of Nrf2 in alveolar macrophages and lung tissues of patients with emphysema was due to an increase of Bach-1 and Kelch-like ECH-associated protein 1 or a loss of Nrf2 protein stability." (PMID 32000766, 2020). "Nuclear Factor Erythroid 2-Like 2 (NFE2L2 or NRF2) and its cytosolic repressor Kelch-like ECH-associated protein-1 (KEAP1) regulate transcription of enzymes involved in cellular detoxification processes and Nfe2l2-deficient mice develop tobacco-induced emphysema." (PMID 19671143, 2009). "Bach1 expression along with Keap-1 has been shown to be increased in lung tissue and alveolar macrophages in patients with severe emphysema suggesting increased repression of anti-oxidant genes in COPD." (PMID 35441963, 2022). "Mechanistically, SESN2 inhibited platelet-derived growth factor receptor β-mediated lung regeneration and injury repair by promoting autophagic degradation of Keap1 to activate the Nrf2–Keap1 pathway that protected against pulmonary emphysema." (PMID 31867002, 2019). "Future research could address this by building on evidence that DMF stabilizes Nrf2 by modifying Keap1 in pulmonary emphysema." (PMID 41009045, 2025). "Animal and human studies have demonstrated that Nrf2/Keap-1 and their target genes protect against inflammation and oxidative stress from cigarette smoke, with Nrf2 disruption in mice leading to increased cigarette smoking-induced emphysema." (PMID 35441963, 2022).
endometrial cancer (7 papers, 2017 to 2024). Primary or metastatic malignant neoplasm involving the endometrium (mucous membrane that lines the endometrial cavity). "Our group has previously reported Keap1 overexpression to be associated with poor prognosis in endometrial cancer." (PMID 39040459, 2024). "Other interesting findings from the NGTS were: (i) frequent detection of RNF43 mutations in both dVIN and de-VIL, which have been previously associated with endometrial carcinoma, and (ii) detection of mutations in KEAP1, CDH1, PIK3R1, and POLE exclusively in de-VIL." (PMID 33918187, 2021). "According to earlier studies involving patients with endometrial cancer, strong Nrf2 and Keap1 expression is related to poorer prognosis." (PMID 39040459, 2024). "An association between Keap1 expression and poor prognosis was also demonstrated in endometrial cancers, and the authors postulated that the overexpression of Keap1 may reflect Keap1 induction in the setting of oxidative stress." (PMID 32751896, 2020). "This is in agreement with previous experimental results in endometrial cancer research, which suggest that Nrf2 protein expression levels may be more strongly affected by the ubiquitination degradation mediated by Keap1, than by transcription and translation.." (PMID 28817677, 2017).
ischemia (7 papers, 2016 to 2024). A hypoperfusion of the BLOOD through an organ or tissue caused by a PATHOLOGIC CONSTRICTION or obstruction of its BLOOD VESSELS, or an absence of BLOOD CIRCULATION. "Studies have shown that in mice with renal tubule-specific knockout of Keap1, moderate activation of Nrf2 might reduce the damage caused by ischemia or nephrotoxic substances, while excessive and continuous activation of Nrf2 loses this protective effect." (PMID 35145414, 2022). "The modulation of Nrf2/Keap1/HO-1 signaling is known to regulate cardiac ischemia-reperfusion injury, hypertensive heart disease, coronary heart disease, and arrhythmia." (PMID 33312223, 2020). "During ischemia, the expression level of Nrf2 is enhanced, and it is partly released from Keap1 and translocated to the nucleus, where it triggers the expression of several dozen cytoprotective proteins, such as HO-1 and NAD(P)H." (PMID 27965540, 2016). "Additionally, it has been suggested that the Keap1/Nrf2 system contributes to the protection in pathologies like DM and ischemia." (PMID 33505452, 2021).
kidney damage (7 papers, 2017 to 2025). "Nevertheless, it has been proven in animal models that astaxanthin has a protective effect on kidney damage by regulating inflammation (inducing CD8+ T cells) and oxidative stress-related NRF2/KEAP1 and ROS pathways." (PMID 34684678, 2021). "In a mouse model of ischemia-reperfusion injury- (IRI-) induced kidney damage, the maximal response of NQO1 mRNA to IRI was an ~1.8-fold increase in wild-type mice and a 5-fold increase in KEAP1-knockdown mice." (PMID 28785379, 2017).
acute pancreatitis (6 papers, 2021 to 2025). An acute inflammatory process that leads to necrosis of the pancreatic parenchyma. "For example, in a rat model of severe acute pancreatitis, cinobufagin exhibited potent antioxidant effects by inhibiting the Keap1-Nrf2 interaction and promoting HO-1 expression." (PMID 41300515, 2025). "Additionally, emodin-mediated activation of the Nrf2/Keap1 pathway further emphasizes its role in mitigating oxidative damage and reducing inflammation markers in severe acute pancreatitis models." (PMID 40076558, 2025). "FMT in rats treated with Saikosaponin A could alleviate severe acute pancreatitis by activating the Keap1/Nrf2-ARE antioxidant signaling pathway." (PMID 39682952, 2024).
amyotrophic lateral sclerosis (6 papers, 2009 to 2026). Amyotrophic lateral sclerosis (ALS) is a neurodegenerative disease characterized by progressive muscular paralysis reflecting degeneration of motor neurons in the primary motor cortex, corticospinal tracts, brainstem and spinal cord. "mRNA expression of the Kelch-like ECH-associated protein 1 (Keap1) was increased in the primary motor cortex in samples from amyotrophic lateral sclerosis patients, suggesting that this may contribute to chronic motor neuron degeneration." (PMID 19859546, 2009). "Activation of the KEAP1/NRF2 pathway blocks the progression of degenerative diseases such as AD and amyotrophic lateral sclerosis (ALS)." (PMID 35463999, 2022).
autoimmune disease (6 papers, 2018 to 2024). A disorder resulting from loss of function or tissue destruction of an organ or multiple organs, arising from humoral or cellular immune responses of the individual to their own tissue constituents. "Coumarin acts on immune cells and cytokines and plays a role in the treatment of autoimmune diseases by regulating NF-κB, Keap1/Nrf2, MAPKs, JAK/STAT, Wnt/β-catenin, PI3K/AKT, Notch and TGF-β/Smad signaling pathways." (PMID 39544933, 2024). "In addition, the Keap1-Nrf2 system has recently emerged as an important therapeutic target in the treatment of a variety of diseases, including cancer, neurological disorders, autoimmune diseases, and inflammatory conditions." (PMID 35993016, 2022). "(iv) The majority of the patents related to Nrf2 and autoimmune diseases from 2017–2020 focus on the use of nonelectrophilic Nrf2 pathway activators, which are shown or postulated to directly inhibit the Keap1–Nrf2 protein–protein interaction." (PMID 33212784, 2020).
malnutrition (6 papers, 2006 to 2024). Inadequate nutrition resulting from poor diet, malabsorption, or abnormal nutrient distribution. "The lethality of Keap1-null mice is however not caused by cell cycle arrest but appears to result from malnutrition." (PMID 16895602, 2006).
non-alcoholic fatty liver disease (6 papers, 2018 to 2025). "In addition, the diterpenoid Dehydroabietic Acid activates the Keap1/Nrf2-ARE signalling pathway and attenuates non-alcoholic fatty liver disease (NAFLD)." (PMID 38846099, 2024).
preeclampsia (6 papers, 2018 to 2024). Preeclampsia is a hypertensive disorder of pregnancy that is characterized by new-onset hypertension with proteinuria presenting after 20 weeks of gestation, and depending on mild or severe forms may initially present with severe headache, visual disturbances, and hyperreflexia. "This KEAP1 inhibition by fetal cells was associated with improved fetal outcomes, suggesting that decidual KEAP1 represents a fetal protective mechanism in preeclampsia; this is a novel observation in humans." (PMID 35216082, 2022). "A microarray meta-analysis of the placenta has shown transcriptional downregulation of Nrf2 and Keap1 in preeclampsia." (PMID 35216082, 2022). "The trophoblast-dependent KEAP1-protein expression in preeclampsia with normal fetal growth indicates control of decidual oxidative stress by maternal–fetal interaction and underscores the importance of discriminating between preeclampsia with and without FGR." (PMID 35216082, 2022). "Preeclampsia combined with FGR was associated with an increased oxidative-stress level and NRF2-regulated gene expression in the decidua, while decidual NRF2- and KEAP1-protein expression was unaffected." (PMID 35216082, 2022). "In preeclampsia, there was increased decidual oxidative stress, NRF2-regulated gene expression was reduced, and KEAP1 protein expression was increased in areas of high trophoblast density." (PMID 38666946, 2024). "Although preeclampsia with normal fetal growth also showed increased decidual oxidative stress, NRF2-regulated gene expression was reduced, and KEAP1-protein expression was increased in areas of high trophoblast density." (PMID 35216082, 2022). "However, prior works have also described altered levels of Keap1 and CUL3 in other pregnancy complications, such as preeclampsia, suggesting its potential role in the pathophysiology of obstetric diseases." (PMID 36421463, 2022). "Increased KEAP1 expression in preeclampsia without FGR, as observed here, potentially counteracts these adverse effects of NRF2 activation." (PMID 35216082, 2022). "We identified FGR-associated regulation of the oxidative-stress response in preeclampsia, as evidenced by increased decidual trophoblast-dependent KEAP1-protein expression in preeclampsia without FGR." (PMID 35216082, 2022). "The decidual expression of KEAP1 was selectively increased in preeclampsia without FGR, potentially resulting in a reduced NRF2/KEAP1 ratio, supporting a net inhibition of NRF2 activation as an explanation for the corresponding reduction in the NRF2-regulated gene expression." (PMID 35216082, 2022). "This study substantiates a divergent regulation of the decidual NRF2-mediated oxidative-stress response in preeclampsia with and without FGR, and suggests that the inhibitor KEAP1 is an important regulator." (PMID 35216082, 2022).
renal cell carcinoma (6 papers, 2016 to 2025). "An increasing body of evidence supports a key role for Keap1/Nrf2 pathway in kidney diseases and renal cell carcinoma (RCC), but data concerning the molecular basis and the clinical effect of its deregulation remain incomplete." (PMID 28061437, 2017). "Since the role of DNA methylation and genes epigenetically altered in RCC have been an active area of research over the past decade, the main purpose of this study is to investigate the contribution of epigenetic deregulation of the KEAP1 gene in different histotypes of renal cell carcinomas." (PMID 28061437, 2017). "However, several studies demonstrated a general high impact of Nrf2 dysfunction in renal cell carcinoma, suggesting that the deregulation of the Keap1 may play a role in carcinogenesis process histotypes beside the presence of genomic alterations." (PMID 28061437, 2017).
triple-negative breast carcinoma (6 papers, 2015 to 2025). An invasive breast carcinoma which is negative for expression of estrogen receptor (ER), progesterone receptor (PR), and human epidermal growth factor receptor 2 (HER2). "In the same paper, Keap1 methylation associated with an increased risk of BCSS in the subset of patients with triple-negative breast cancer." (PMID 29348788, 2017). "Mutated in 20% of human cancers; doxorubicin resistant triple-negative breast cancer is associated with loss of SMARCB1, SMARCA4, or KEAP1 (a BRCA1 interactor)." (PMID 31287417, 2019). "In contrast, we and others have previously shown that there is aberrant Keap1 methylation in triple-negative breast cancer (TNBC) and Keap1 overexpression is associated with poor prognosis in TNBC." (PMID 25879528, 2015). "In triple-negative breast cancer patients with KEAP1 methylation, a higher mortality risk was observed than in patients without triple-negative breast cancer." (PMID 31159323, 2019).